MDM2 (MDM2 proto-oncogene)
Diseases named in the same sentence as MDM2 in open-access papers (continued):
Sharing a sentence is not in itself a finding about the gene and the disease.
cancer (continued). "Overall, these findings highlight the impact of 3’UTRs and RNA editing on protein levels of MDM2 and potentially other cancer-related genes." (PMID 40381037, 2025). "Since its discovery, there have been extensive investigations into the discovery and development of MDM2 inhibitors for cancer therapy." (PMID 40046748, 2025). "The novel MDM2 inhibitor MA242 effectively disrupts these metabolic pathways, illustrating the pivotal role of MDM2 in supporting cancer cell proliferation and survival." (PMID 40046748, 2025). "Based on these studies, MDM2 has been identified as a recognized oncogene, which is involved in the regulation of the occurrence and development of a variety of cancers." (PMID 40264676, 2025). "USP7 is critically involved in cancer development, mediating the deubiquitylation (and therefore the stabilization) of oncogenic proteins such as MDM2 and c-Myc, and influencing growth factor TGF-β, which promotes cell survival and proliferation." (PMID 41157055, 2025). "Currently, clinical trials on the development of MDM2 inhibitors for cancer therapy are evaluating various compounds." (PMID 41515979, 2025). "This dual functionality establishes MDM2 inhibition as a versatile therapeutic strategy with broad relevance across diverse cancer types, driving ongoing research into novel inhibitors and rational combination therapies." (PMID 41170373, 2025). "CHIP was highly expressed in most cancer types, and MDM2, RNF14, and RNF4 were expressed in most tumors." (PMID 41194439, 2025). "Collectively, an MDM2 amplification was present in 27% of pleomorphic adenoma (4 of 15), compared to 78% of carcinoma ex pleomorphic adenoma (14 of 18) (p-value = 0.003)." (PMID 40338436, 2025). "Our results contribute to the elucidation of the MDM2 stabilization mechanism in cancer cells, expanding our understanding of the new functions of RPs." (PMID 39199272, 2024). "In summation, these in vivo data corroborate the notion that the combination of MDM2 inhibitors and TOP2β poisons has excellent in vivo anti-cancer efficacy." (PMID 38263255, 2024).
cancer (continued). "Results from TUNEL assay also yielded cancer cells responded to Osimertinib and underwent apoptosis after MDM2 depletion." (PMID 39543744, 2024). "To further explore the USP7‐dependent, MDM2‐independent mechanism of action in fibroblasts, we performed a differential gene expression analysis in cancer cells versus fibroblasts." (PMID 38602256, 2024). "The patients with high‐mRNA expression levels of either USP7 or MDM2 had a short survival period and obvious cancer‐promoting characteristics, while patients with high expression levels of DICER had longer survival and cancer suppression characteristics." (PMID 37867415, 2024). "It is worth noting that compared with other DNA-damaging agents, cancer cells exhibiting MDM2 overexpression are preferentially resistant to TOP2 poisons, and have decreased DNA DSBs in response to etoposide." (PMID 38263255, 2024). "The murine double minute 2 (MDM2) proto-oncogene plays a crucial role in cancer development including promoting cell proliferation, apoptosis evasion, metastasis, and chemotherapy resistance." (PMID 39410536, 2024).
cancer (continued). "Recently, therapeutic strategies targeting MDM2 have shown great promise in cancer, as evidenced by numerous clinical trials." (PMID 39143552, 2024). "MDM2 promoted resistance to Osimertinib through a PI3K/Akt and MAPK/Erk-independent machinery, in contrast, MDM2 selectively stabilized MCL-1 protein to arrest Osimertinib-induced cancer cell apoptosis." (PMID 39543744, 2024). "Genetic variation in MDM2 promotes its increased expression levels, which leads to uncontrolled proliferation in many cancer types." (PMID 38893137, 2024). "Several recent reviews have comprehensively discussed the function of MDM2 in tumorigenesis, its amplification and expression in diverse human cancers, and the cancer therapeutic agent that specifically target MDM2 protein." (PMID 38640125, 2024). "It seems this drug was unable to reduce the expression of MDM2 gene significantly in triple negative (MDA-MB-231) cancer cells; however, a decrease was observed in luminal A (MCF-7) cells." (PMID 39116089, 2024). "Taken together, our results suggest a novel strategy to enhance the effectiveness of TOP2-targeted anti-cancer therapies and reduce side effects by combining them with MDM2 inhibitors to prevent TOP2βcc proteolysis." (PMID 38263255, 2024).
cancer (continued). "The MDM2 protein is a well-studied oncogene product with a crucial function in cancer cell survival, invasiveness, and therapeutic resistance." (PMID 38263255, 2024). "Translation of preclinical results to clinical success for MDM2 inhibitors has been unsuccessful to date for adult cancers." (PMID 39510293, 2024). "Much evidence suggests that MDM2 is overexpressed in many human tumors and promotes cancer progression and drug resistance." (PMID 39199272, 2024). "Cancer cells with aberrant MDM2 state are refractory to apoptosis induction and elicit a resistant phenotype to Osimertinib." (PMID 39543744, 2024). "Insufficient clinical responses to monotherapy MDM2 inhibitors in other cancers prompted us to explore optimal drugs for combination therapy." (PMID 38600316, 2024). "Inhibiting MDM2 can enhance the sensitivity of cancer cells to radiation, improving the effectiveness of radiotherapy." (PMID 39498386, 2024). "There is a growing body of investigation currently underway on MDM2 inhibitors in clinical trials, reflecting the increasing interest in including these drugs in cancer treatment regimens." (PMID 39061962, 2024).
cancer (continued). "The inhibition of MDM2 can significantly repress the proliferation of cancer cells, and eight inhibitors targeting MDM2 have been developed for several solid tumors and hematological malignancies." (PMID 38862432, 2024). "In order to find the molecular mechanism by which PURPL can regulate nuclear morphology or chromosomal stability, we focused on MDM2 for the following reasons: The MDM2 gene was subsequently found to be amplified in cancer." (PMID 39763585, 2024). "Indisputable preclinical and clinical data demonstrate that targeting MDM2 treatment is a newly discovered approach that can enhance both the effectiveness and safety of cancer therapeutics." (PMID 38281981, 2024). "Targeting MDM2 presents a promising approach to surmounting immunotherapy resistance, thereby offering opportunities for cancer treatment." (PMID 38281981, 2024). "This case underscores the importance of combining histopathology, immunohistochemistry (IHC), and molecular testing, particularly murine double minute clone 2 (MDM2) amplification, to distinguish between benign and malignant tumors." (PMID 39525228, 2024). "ALRN-6924, an MDM2/4 antagonist currently in clinical trials, is administered intravenously, but clinical use of subcutaneous injections for anti-cancer agents like Trastuzumab and Methotrexate demonstrates the clinical applicability of this route." (PMID 37823909, 2024). "S6K1 signaling was constitutively activated in resistant cancer cells, and MDM2 was a functional effector of S6K1 in mediating EGFR-TKI resistance." (PMID 38397056, 2024). "At the post-translational level, MDM2 also serves as a crucial protein biomarker involved in the cellular response to IR exposure, potentially contributing to cancer development and metastasis." (PMID 39498386, 2024). "FKBP12 containing one PPIase domain binds to oncoprotein MDM2 and induces MDM2 degradation to enhance the sensitivity of chemotherapy in cancer." (PMID 39281835, 2024).